ZKSCAN8P1 (ZKSCAN8 pseudogene 1)
Synonyms: dJ265C24.4; ZNF389P; ZNF192P1; ZNF389
Gene: Protein-coding gene on chromosome 6 (28,161,769 to 28,169,594, forward strand). Ensembl gene ENSG00000226314.
Gene Ontology:
Cellular component: nucleus
Homologues: Orthologues: macaque ZNF389 (97% identical), pig ZNF389 (92% identical). Paralogues in human: ZNF135 (55% identical), ZNF250 (55% identical), ZNF3 (55% identical), ZFP2 (54% identical), ZNF16 (54% identical), ZNF383 (54% identical), ZNF391 (54% identical), ZFP3 (53% identical), ZNF30 (53% identical), ZNF182 (53% identical), ZNF41 (53% identical), ZNF543 (53% identical), and 164 more.
Diseases named in the same sentence as ZKSCAN8P1 in open-access papers:
ZKSCAN8P1 is named in the same sentence as 4 diseases in open-access papers, as found by Europe PMC text mining. Sharing a sentence is not in itself a finding about the gene and the disease. The quoted sentences say what the papers report.
migraine with aura (1 paper, 2025). A migraine disorder characterized by episodes that are preceded by focal neurological symptoms. "SMR and INTACT confirmed the validity of BLM, C12orf76, GPATCH4, PAM, SERPINC1 for migraine, and ALMS1, GPATCH4, NCF2, SLC12A1, ZKSCAN8P1 for migraine with aura." (PMID 41261954, 2025). "The results of the SMR, colocalization, and INTACT sensitivity analyses provided further validation of BLM, C12orf76, GPATCH4, PAM, SERPINC1 as contraindicated drugs’ target genes for migraine, and ALMS1, GPATCH4, NCF2, SLC12A1, ZKSCAN8P1 for migraine with aura." (PMID 41261954, 2025). "For migraine with aura, SERPINC1, ALMS1, ZKSCAN8P1, PAM, and NCF2 were significant (p < 0.05); SERPINC1 was significant in nine regions, with the most pronounced association in the Nucleus accumbens (basal ganglia) (p = 0.014)." (PMID 41261954, 2025). "At the brain‐tissue level, we further validated hub gene associations: in migraine, SERPINC1, ZKSCAN8P1, C12orf76, and PAM were significant across brain regions; in migraine with aura, SERPINC1, ALMS1, ZKSCAN8P1, PAM, and NCF2 were significant." (PMID 41261954, 2025).
ZKSCAN8P1 also shares sentences with these, for which no sentence is quoted: depression (1 paper); gastric cancer (1); infection (1).